ARL6IP4 (ARF like GTPase 6 interacting protein 4)
Description:
Involved in modulating alternative pre-mRNA splicing with either 5' distal site activation or preferential use of 3' proximal site. In case of infection by Herpes simplex virus (HSVI), may act as a splicing inhibitor of HSVI pre-mRNA.
Synonyms: SR-25; SRp25; SFRS20; SRrp37
Tractability: PROTAC: UniProt records ubiquitination sites on it; ubiquitination databases record sites on it; its protein half-life has been measured.
Gene: Protein-coding gene on chromosome 12 (122,980,045 to 122,983,479, forward strand). Ensembl gene ENSG00000182196.
Subcellular location: Nucleus, nucleolus; Nucleus speckle
Subcellular location (Human Protein Atlas): Nucleoplasm; Mitochondria
Gene Ontology:
Molecular function: protein binding; RNA binding
Biological process: RNA splicing
Cellular component: nucleus; nuclear speck; nucleolus
Genetic constraint (gnomAD): Loss-of-function variants: 24 observed, 26.42 expected, observed/expected ratio (o/e) 0.91, 90% interval 0.66 to 1.28. The synonymous counts are far from expectation, so gnomAD's model fits this gene poorly and the ratio says little. Missense variants: 343 observed, 295.57 expected, observed/expected ratio (o/e) 1.16, 90% interval 1.06 to 1.27. Synonymous variants: 162 observed, 120.24 expected, observed/expected ratio (o/e) 1.35, 90% interval 1.18 to 1.53.
Homologues: Orthologues: chimpanzee ARL6IP4 (98% identical), macaque ARL6IP4 (91% identical), pig ARL6IP4 (90% identical), dog ARL6IP4 (85% identical), guinea pig ARL6IP4 (83% identical), mouse Arl6ip4 (81% identical), rat Arl6ip4 (77% identical), tropical clawed frog arl6ip4 (56% identical), zebrafish arl6ip4 (41% identical), Drosophila melanogaster CG18428 (29% identical).
Diseases named in the same sentence as ARL6IP4 in open-access papers:
ARL6IP4 is named in the same sentence as 8 diseases in open-access papers, as found by Europe PMC text mining. Sharing a sentence is not in itself a finding about the gene and the disease. The quoted sentences say what the papers report.
Obesity (1 paper, 2022). Accumulation of substantial excess body fat. "A study on the shared risk of schizophrenia and cardiometabolic diseases including obesity, body mass index, and type 2 diabetes suggested that MPHOSPH9, ARL6IP4, and SETD8 are pleiotropic risk genes." (PMID 36174000, 2022).
viral infection (1 paper, 2022). "Interestingly, we found that the ubiquitination of many host proteins that interact with SARS-CoV-2 was also changed after viral infection, such as ZDHHC5, BUD31, SCP2, ARL6IP4, and NUDCD2, which were reported to interact with the SARS-CoV-2 Spike protein." (PMID 36071039, 2022).
cancer (1 paper, 2025). A tumor composed of atypical neoplastic, often pleomorphic cells that invade other tissues. "However, the expression and role of ARL6IP4 in cancer, particularly in CRC, remain rarely explored." (PMID 41567198, 2025). "In our eight signature genes (ARL6IP4, ATP2A1, CRYAB, ELFN2, MAP2, MAT1A, ORC1, and POU4F1), prior research has elucidated the expression and function of several genes involved in the initiation and progression of cancer." (PMID 41567198, 2025).
tumor (1 paper, 2024). "Validation analysis confirmed the up-regulation of model genes, including AKR1B10, ARL6IP4, ATP6V0B, and BSG in tumor tissues." (PMID 38913193, 2024). "In the TCGA dataset, the expression levels of AKR1B10, ARL6IP4, ATP6V0B, and BSG were significantly up-regulated in the tumor samples." (PMID 38913193, 2024).
ARL6IP4 also shares sentences with these, for which no sentence is quoted: colorectal cancer (1 paper); infection (1); schizophrenia (1); type 2 diabetes (1).